SPR (sepiapterin reductase)
Description:
Catalyzes the final one or two reductions in tetra-hydrobiopterin biosynthesis to form 5,6,7,8-tetrahydrobiopterin.
Synonyms: SDR38C1
Tractability: Small molecule: a structure with a bound ligand is known; a high-quality ligand is known; it has a high-quality binding pocket. PROTAC: ubiquitination databases record sites on it; its protein half-life has been measured; a small molecule that binds it is known.
Target class: Enzyme; Oxidoreductase
Gene: Protein-coding gene on chromosome 2 (72,887,379 to 72,892,158, forward strand). Ensembl gene ENSG00000116096.
Subcellular location: Cytoplasm
Subcellular location (Human Protein Atlas): Cytosol; Nucleoplasm
Pathways (Reactome):
Metabolism: Tetrahydrobiopterin (BH4) synthesis, recycling, salvage and regulation; eNOS activation
Gene Ontology:
Molecular function: sepiapterin reductase (NADP+) activity; alcohol dehydrogenase (NADP+) activity; NADP binding; oxidoreductase activity, acting on the CH-OH group of donors, NAD or NADP as acceptor
Biological process: nitric oxide biosynthetic process; tetrahydrobiopterin biosynthetic process
Cellular component: cytosol; extracellular exosome; mitochondrion; cytoplasm
Genetic constraint (gnomAD): Loss-of-function variants: 15 observed, 15.06 expected, observed/expected ratio (o/e) 1, 90% interval 0.67 to 1.53. The synonymous counts are far from expectation, so gnomAD's model fits this gene poorly and the ratio says little. Missense variants: 324 observed, 291.26 expected, observed/expected ratio (o/e) 1.11, 90% interval 1.01 to 1.22. Synonymous variants: 177 observed, 135.4 expected, observed/expected ratio (o/e) 1.31, 90% interval 1.16 to 1.48.
Gene-disease validity (ClinGen):
ClinGen rates the evidence that SPR causes each of these diseases.
dopa-responsive dystonia due to sepiapterin reductase deficiency (autosomal recessive): Definitive. Dopa responsive dystonia (DRD) due to sepiapterin reductase deficiency (SRD) is a very rare neurometabolic disorder characterized by dystonia with diurnal fluctuations, axial hypotonia, oculogyric crises, and delays in motor and cognitive development.
Homologues: Orthologues: chimpanzee SPR (99% identical), macaque SPR (97% identical), rabbit SPR (86% identical), pig SPR (84% identical), dog SPR (84% identical), guinea pig SPR (82% identical), mouse Spr (75% identical), rat Spr (74% identical), rat Spr-ps1 (67% identical), tropical clawed frog spr (58% identical), zebrafish spra (52% identical), zebrafish sprb (50% identical), and 2 more.
Diseases named in the same sentence as SPR in open-access papers:
SPR is named in the same sentence as 52 diseases in open-access papers, as found by Europe PMC text mining. Sharing a sentence is not in itself a finding about the gene and the disease. The quoted sentences say what the papers report.
dopa-responsive dystonia (15 papers, 2013 to 2024). "Dopa-responsive dystonia due to sepiapterin reductase deficiency (OMIM#612716) is caused by recessive mutations in the gene encoding sepiapterin reductase (SPR), which plays an important role in the biosynthesis of tetrahydrobiopterin (BH4)." (PMID 31777525, 2019). "Previous studies found that mutations in SPR (sepiapterin reductase) result in DOPA-responsive dystonia." (PMID 27657167, 2016). "Moreover, mutations in genes involved in the biosynthesis of DA encoding GTP cyclohydroxylase (DYT5), sepiapterin reductase and tyrosine hydroxylase cause dopa-responsive dystonia." (PMID 27716431, 2016). "Mutations in the gene SPR result in a second form of autosomal recessive DOPA-responsive dystonia." (PMID 23775978, 2013). "To date, three genes have been convincingly shown to cause DOPA-responsive dystonia: GCH1 (GTP cyclohydrolase 1), TH (tyrosine hydroxylase) and SPR (sepiapterin reductase)." (PMID 23775978, 2013). "Interestingly, a similar defect or delay in neuronal maturation has been described in the human disease Dopa Responsive Dystonia (DRD), characterised by dopamine deficiency as a result of a germline mutation in one of the BH4 or TH processing enzymes such as GTPCH or sepiapterin reductase." (PMID 38042898, 2023).
Dystonia (8 papers, 2017 to 2025). An abnormally increased muscular tone that causes fixed abnormal postures. "A deficiency in SPR has been clinically linked to symptoms of dystonia, and speech and motor development issues." (PMID 40422884, 2025). "Sepiapterin reductase deficiency is clinically known to produce symptoms of dystonia, and speech and motor development issues." (PMID 40422884, 2025). "SPR deficiency occurs due to SPR gene mutation and causes an inherited pediatric movement disorder called dystonia." (PMID 36499560, 2022). "The identified variant in this study is novel in the gene SPR and is supposed to cause the disease: dystonia, dopa-responsive, due to sepiapterin reductase deficiency (OMIM#612716)." (PMID 31777525, 2019). "This study proposes a novel loss of function variant that leads to a truncated protein as causative of the autosomal recessive dystonia, dopa-responsive, due to sepiapterin reductase deficiency." (PMID 31777525, 2019). "Dystonia with parkinsonism includes DRD [DYT5, tyrosine hydroxylase (TH), and sepiapterin reductase (SPR)], dopamine agonist-responsive dystonia, rapid-onset dystonia parkinsonism (DYT12), and early-onset dystonia with parkinsonism (DYT16)." (PMID 32117556, 2019). "In addition to these 45 individuals, we identified ten carriers of single heterozygous pathogenic variants in recessively inherited dystonia genes, including AOPEP (n=5), SPR (n=4), and HPCA (n=1)." (PMID 40672488, 2025). "Additionally, likely pathogenic or pathogenic variants were found in ATP1A3 (n = 5) and GNAO1 (n = 1) for genes causing combined dystonia, as well as ACTB (n = 1), IRF2BPL (n = 1), SPR (n = 1), and TUBB4A (n = 3) for genes linked to dystonia with other neurological or systemic features." (PMID 40533913, 2025).
neuroblastoma (8 papers, 2015 to 2023). Neuroblastoma (NB) is the most common solid, extracranial childhood tumor. "Recently, there have been several reports showing how SPR promotes cancer progression in neuroblastoma, hepatocelluar carcinoma, as well as breast and ovarian cancers." (PMID 37251335, 2023). "The overexpression of SPR mRNA was also found in neuroblastoma, breast cancer, and hepatocarcinoma cells." (PMID 34502464, 2021). "Lipopolysaccharide treatment has resulted in the up‐regulation of SPR gene expression in the murine neuroblastoma (NB) cell line N1E‐115 62 and the striatum, while this effect of lipopolysaccharide has not been achieved in the murine locus coeruleus." (PMID 32734666, 2020). "Recently, Lange et al41 reported an oncogenic role for SPR in neuroblastoma and found that overexpression of SPR mRNA correlates with poor prognosis in patients." (PMID 32536039, 2020). "Indeed, SPR expression is significantly correlated to unfavorable neuroblastoma characteristics such as oncogenic MYC amplification and increased aggressiveness." (PMID 37251335, 2023). "Interestingly, depletion of SPR by siRNA significantly impairs ODC enzyme activity and depletion or pharmacological inhibition of SPR impairs proliferation of neuroblastoma cells suggesting SPR as a potential new regulator of ODC." (PMID 34068137, 2021). "Over expression of SPR mRNA correlated with poor prognosis in neuroblastoma patients." (PMID 32536039, 2020). "Although the roles of the interaction between ODC and SPR remain largely unknown, it is also interesting that combination treatment of the SPR inhibitor sulfasalazine with DFMO shows synergistic antiproliferative effects versus neuroblastoma cells, at least ex vivo." (PMID 34068137, 2021).
Parkinson disease (7 papers, 2017 to 2025). A progressive degenerative disorder of the central nervous system characterized by loss of dopamine producing neurons in the substantia nigra and the presence of Lewy bodies in the substantia nigra and locus coeruleus. "This deficiency of BH4 in Parkinson’s occurs because of the deficiency in the enzyme Sepiapterin Reductase (SPR), which is necessary for conversion of pterins to BH4." (PMID 40422884, 2025). "Thus, many silkworm disease models have been established recently, such as Parkinson’s disease, human sepiapterin reductase deficiency, insulin-related human disease, and Hermansky–Pudlak syndrome." (PMID 29596327, 2018). "The observed deficiencies of MTHFR, MTHFD1, DHFR, SPR and PTPS suggest a direct and critical impact on the choroid plexus in Parkinson’s disease (PD)." (PMID 40422884, 2025). "We suggest an important role of BH4 and SPR in age‐related hypertension and a possible relationship with the cardiovascular instabilities in autonomic diseases, including Parkinson's disease and spinal cord injury." (PMID 28320892, 2017).
Hyperphenylalaninemia (6 papers, 2014 to 2025). "This is enough to provide baseline, physiological activity of PAH in SPR-deficient patients and so, importantly, negating hyperphenylalaninemia development." (PMID 37251335, 2023). "WES analysis has shown that neither of these patients had pathogenic, likely pathogenic, or variants of uncertain significance (VUS) above 50% posterior probability in genes associated with hyperphenylalaninemia (GCH1, PCBD1, PTS, QDPR, SPR and DNAJC12)." (PMID 40473815, 2025). "Hyperphenylalaninemia (HPA) is the first diagnostic hallmark for most BH4 deficiencies, apart from autosomal dominant guanosine triphosphate cyclohydrolase I deficiency and sepiapterin reductase deficiency." (PMID 32456656, 2020). "In addition, as PAH mediates the conversion of phenylalanine (Phe) to tyrosine (Tyr), hyperphenylalaninemia (HPA) is present in all BH4 deficiencies apart from autosomal dominant guanosine triphosphate cyclohydrolase I deficiency (AD-GTPCHD) and sepiapterin reductase deficiency (SRD)." (PMID 32456656, 2020). "Mice lacking SPR have a defect in brain serotonin and dopamine levels but also hyperphenylalaninemia and increased blood pressure and arrhythmia." (PMID 37251335, 2023). "The clinical picture of patient number 6 pointed to l-dopa responsive dystonia without hyperphenylalaninemia, which may occur in autosomal dominant GTPCH I deficiency, sepiapterin reductase (SR) deficiency, or in tyrosine hydroxylase (TH) deficiency." (PMID 24949445, 2014).
hepatocellular carcinoma (4 papers, 2020 to 2024). A malignant tumor that arises from hepatocytes. "Here, we found that sepiapterin reductase was frequently highly expressed in human hepatocellular carcinoma, which was significantly associated with higher T stage, higher tumor node metastasis stage, and even shorter survival of hepatocellular carcinoma patients." (PMID 32312975, 2020). "In hepatocellular carcinoma (HCC), elevated SPR expression is significantly associated with shorter patient survival, suggesting that SPR could serve as a potential prognostic marker for HCC." (PMID 39659787, 2024). "Moreover, we showed that sepiapterin reductase regulated the development of hepatocellular carcinoma via the FoxO3a/Bim-signaling pathway." (PMID 32312975, 2020). "However, the role of sepiapterin reductase in hepatocellular carcinoma remains largely unknown." (PMID 32312975, 2020). "Collectively, our study suggests that sepiapterin reductase controls hepatocellular carcinoma progression via FoxO3a/Bim signaling in a nonenzymatic manner, which provides a potential prognostic factor and therapeutic strategy for hepatocellular carcinoma." (PMID 32312975, 2020). "Importantly, the results suggested that sepiapterin reductase enzymatic activity was not necessary for the progression of hepatocellular carcinoma, based on the comparison between SMMC-7721 and SMMC-7721 containing sepiapterin reductase mutant." (PMID 32312975, 2020).
melanoma (3 papers, 2014 to 2022). A malignant, usually aggressive tumor composed of atypical, neoplastic melanocytes. "Of note, the 3 SPR-proficient melanoma strains exhibited significantly higher fold-inductions (range 4.0±0.3–5.0±0.7) relative to 9 SPR-deficient counterparts (range 2.2±0.1–3.4±0.3) (p<0.002, student t test)." (PMID 24416382, 2014). "We compared ATR protein levels in the SPR-proficient vs -deficient melanoma strains by Western blotting." (PMID 24416382, 2014). "However we show here that one among the eleven SPR-deficient melanoma strains, i.e., WM3248, display greatly reduced ATR protein levels compared with SPR proficient counterparts." (PMID 24416382, 2014). "Normal melanocytes exhibited γH2AX induction levels comparable to those of SPR-proficient melanoma strains (range 4.2±0.2–5.1±0.5)." (PMID 24416382, 2014). "We next investigated whether defective SPR in melanoma cell lines might be correlated with reduced ATR activity." (PMID 24416382, 2014). "Since our three SPR-proficient melanoma strains all express functional PTEN, we initially speculated that downregulation of this tumour suppressor might abrogate NER in melanoma cells possibly in an S phase-specific manner." (PMID 24416382, 2014). "Moreover, in line with our previous study in primary human lung fibroblasts, we provide evidence that defective SPR in melanoma cells correlates with reduced activation post-UV of ATR kinase, a master regulator of the cellular response to DNA damage-induced replication stress." (PMID 24416382, 2014). "Moreover, public data from Oncomine and TCGA showed that high GCH1 expression correlates with melanoma aggressiveness, increased expression of PTS and SPR, and decreased GCHFR expression in melanoma when compared to benign nevi." (PMID 34502464, 2021). "Although WM1552C cells present a prooxidant status, the high expressions of SPR, DHFR and DHPR found in these melanoma cells (data not shown) can prevent BH4 oxidation and avoid a complete BH4 loss." (PMID 35682659, 2022).
Hypertension (2 papers, 2017 to 2020). The presence of chronic increased pressure in the systemic arterial system. "Moreover, the therapeutic effects of sepiapterin, a substrate of SPR, in hypertension depend on the level of SPR in the arteries." (PMID 32734666, 2020). "Therefore, strategies specifically targeting SPR might be necessary for restoring NOS function in different types of hypertension." (PMID 32734666, 2020). "After weaning, SPR‐/‐ but not SPR+/− adult mice suffered from hypertension with fluctuation and bradycardia due to the decrease in endothelium‐dependent relaxation." (PMID 32734666, 2020).
liver cancer (2 papers, 2020). An epithelial or non-epithelial malignant neoplasm that arises from the liver. "For example, we found that the enhancer probe cg04161113, whose activation (low DNA methylation) is associated with poor survival, is potentially regulating the SPR gene, which was recently reported as an oncogene in liver cancer." (PMID 32925947, 2020). "A recent study showed that SPR depletion inhibited liver cancer cell proliferation and promoted cancer cell apoptosis in vivo, suggesting its role as an oncogene." (PMID 32925947, 2020). "Furthermore, we analyzed SPR expression levels by immunohistochemistry on a tissue microarray containing 97 liver cancer tissues and 89 adjacent liver tissues." (PMID 32312975, 2020).
Arrhythmia (1 paper, 2023). Any cardiac rhythm other than the normal sinus rhythm. "A recent study indicated SPR KO mice also display increased blood pressure and arrhythmia." (PMID 37251335, 2023).
autoimmune disease (1 paper, 2023). A disorder resulting from loss of function or tissue destruction of an organ or multiple organs, arising from humoral or cellular immune responses of the individual to their own tissue constituents. "We have described what we see as the therapeutic potential for peripherally restricted SPR inhibitors as non-opioid chronic pain therapeutics as well as for treatments of certain autoimmune diseases and forms of cancer." (PMID 37251335, 2023).
Chorea (1 paper, 2022). Chorea (Greek for 'dance') refers to widespread arrhythmic involuntary movements of a forcible, jerky and restless fashion. "In contrast, a mildly impaired but independent gait pattern was commonly observed in patients with drug‐responsive neurotransmitters defects (GCH1, DHPR, SPR, TH, and PTPS), nonprogressive chorea (NKX2." (PMID 36054588, 2022).
Cognitive impairment (1 paper, 2025). Abnormal cognition is characterized by deficits in thinking, reasoning, or remembering. "Sepiapterin Reductase Deficiency (SRD) is a rare inherited neurometabolic disorder caused by variants in the SPR gene, which may lead to developmental delays, psychomotor retardation, and cognitive impairments." (PMID 40243727, 2025).
colon carcinoma (1 paper, 2014). "However we provide evidence that PTEN depletion in SPR-proficient WM35 and WM1366, or complete loss of PTEN in colon carcinoma cells, exerts no apparent influence on the removal of either 6–4PPs or CPDs." (PMID 24416382, 2014).
diabetes (1 paper, 2022). "Silkworms contain 5006 genes that are highly homologous to human pathogenic genes and have been developed as models for a variety of human diseases, including sepiapterin reductase deficiency, diabetes, gout, epilepsy, and other neurodegenerative diseases." (PMID 36303171, 2022).
dominant Parkinson’s disease (1 paper, 2022). "Interestingly, the SPR gene is localized in the autosomal dominant Parkinson’s disease-3 (PARK3) locus, and there is accumulated evidence suggesting its association to early-onset PD." (PMID 35330074, 2022).
glioma (1 paper, 2019). A benign or malignant brain and spinal cord tumor that arises from glial cells (astrocytes, oligodendrocytes, ependymal cells). "Survival analysis also demonstrated that, similar to our published findings with GCH1, elevated expression of SPR or DHFR correlated with worse survival of glioma patients." (PMID 31500569, 2019). "Primary data in GlioVis used to generate the survival curves demonstrating that elevated SPR mRNA expression correlates with poor glioma patient survival." (PMID 31500569, 2019). "Our analysis using the HPA datasets showed that, while SPR expression was relatively consistent between normal brain and tumor tissues, the other three members of the pathway were expressed at higher levels in glioma tumors than in normal cells." (PMID 31500569, 2019).
inflammatory bowel disease (1 paper, 2024). A spectrum of small and large bowel inflammatory diseases of unknown etiology. "Clinical data show significant reductions in both pain and inflammation in RA and inflammatory bowel disease patients treated with sulfasalazine, an inhibitor of sepiapterin reductase leading to reduced BH4 levels." (PMID 37814020, 2024).
major depression (1 paper, 2014). "Therefore, PDIA3, SPR, and the other proteins identified might provide a link to the possible psychopathology of major depression." (PMID 24383611, 2014).
microcephaly (1 paper, 2022). A congenital or acquired developmental disorder in which the circumference of the head is smaller than normal for the person's age and sex.
pharyngitis (1 paper, 2015). Inflammation of the throat most often caused by viral and bacterial infections. "Moreover, a well-known herbs in treating inflammation, such as pharyngitis and pneumonia, Terminalia chebula Retz (U00184) is found associated with Sepiapterin reductase, an enzyme that responsible for nitric oxide biosynthetic process, thus, it may also be applied in CVD treatment." (PMID 25970778, 2015).
retinal degeneration (1 paper, 2025). Degeneration of the retina. "The higher transduction efficiency of the outer retinal layer with AAV8 relative to AAV.SPR-, AAV11-, and AAV2-based vectors via the intravitreal route in our study may facilitate the treatment of retinal degeneration mainly with photoreceptor defects." (PMID 40793790, 2025).